AFF4 (ALF transcription elongation factor 4)
Diseases named in the same sentence as AFF4 in open-access papers (continued):
Sharing a sentence is not in itself a finding about the gene and the disease.
pancreatic cancer (1 paper, 2023). "Given the oncogenic role of AFF4 has been well-explored, our study offers a therapeutic target for pancreatic cancer progression." (PMID 37063434, 2023). "In this study, a series of functional experiments established the oncogenic role of AFF4 in pancreatic cancer." (PMID 37063434, 2023). "Together, robust expression of AFF4 sustains multiple kinds of cancer progression, however, the role of AFF4 in pancreatic cancer remains unclear." (PMID 37063434, 2023).
pancreatic ductal carcinoma (1 paper, 2023). "In present study, we observed AFF4 overexpression promoted cell proliferation, colony formation and cell cycle progression while loss of AFF4 impairs above phenotypes of pancreatic ductal carcinoma (PDAC) cells." (PMID 37063434, 2023).
periodontal diseases (1 paper, 2020). "Our study on the molecular mechanism of AFF4 in regulating DFC osteogenic differentiation and its key role in determining the fate of stem cells can provide an important experimental basis for the clinical treatment of bone repair and reconstruction in periodontal diseases." (PMID 32606293, 2020).
periodontitis (1 paper, 2024). An acute or chronic inflammatory process that affects the tissues that surround and support the teeth. "On the one hand, immunohistochemical analysis of PDL tissues revealed that AFF4 proteins were down‐expressed in periodontitis populations, in accordant with osteogenic proteins." (PMID 37731335, 2024). "The present study shows that AFF4 protein expression was significantly lower in periodontitis tissues than healthy periodontal tissues." (PMID 37731335, 2024). "Immunohistochemical staining demonstrated that the periodontitis group showed increased expression of the inflammatory marker (TNFα), along with decreased levels of AFF4 and osteogenic protein (RUNX2, COL1A1)." (PMID 37731335, 2024). "First, AFF4 expression profile was evaluated in conditions of periodontitis and osteogenic differentiation of hPDLSCs by immunohistochemical staining, western blot and qRT‐PCR." (PMID 37731335, 2024). "Therefore, revealing biological actions of AFF4 on osteogenesis of hPDLSCs will not only add to knowledge about how AFF4 regulates systemic bone metabolism, but also help enhance the understanding of periodontitis pathobiology." (PMID 37731335, 2024). "Consistent alteration of AFF4 and osteogenic markers suggests that AFF4 might act as an important regulatory molecule for osteogenesis in condition of periodontitis." (PMID 37731335, 2024). "Reduced expression of AFF4 in PDL tissues of periodontitis implicates that AFF4 might participate in periodontal dyshomeostasis in the condition of periodontitis." (PMID 37731335, 2024).
virus infection (1 paper, 2022). "AFF4 functions in development besides its important role in cancer and virus infection." (PMID 36149892, 2022).
cancer (17 papers, 2009 to 2024). A tumor composed of atypical neoplastic, often pleomorphic cells that invade other tissues. "Similar findings in proteins associated with cancer stemness have been published for AF4/FMR2 family member 4 (AFF4) and sex-determining region Y box2 (SOX2) in head and neck squamous cell carcinoma." (PMID 34312483, 2021). "Thus the mutation of key residues on AFF4 dimer interface might be used as indicators of carcinoma development." (PMID 32128251, 2020). "As the special ability of prompting expression, malfunction of SEC contributes to multiple human diseases, including cancers, thus AFF4 was also involved in cancer progression." (PMID 37063434, 2023). "AFF4 is involved in the regulation of cancer cell proliferation, invasion, and survival in vitro, and tumorigenicity in vivo." (PMID 35706403, 2022). "This makes SEC or its central component factor AFF4 a broad-range target for cancer therapeutic interventions." (PMID 35223479, 2022). "To further evaluate the effect of AFF4 depletion on the self-renewal capacity of BCSCs in vivo, we conducted limiting dilution transplantation assay, a method widely used to assess cancer stem cell content." (PMID 32676121, 2020). "Formation of an SEC with AFF1 or AFF4 is a primary control factor in cancer pathogenesis and development." (PMID 32606293, 2020). "However, AFF4 played a major oncogenic role in several cancers, in contrast to its role in OC." (PMID 34686190, 2021). "Meanwhile, METTL3 plays a role in BCa progression by promoting the cancer cell growth and invasion by regulating a network that involves the AF4/FMR2 family member 4 (AFF4), nuclear factor-kappa B (NF-κB), and Myc." (PMID 35148766, 2022). "The genes of CTSZ, AFF4, DHRS2, and HMGCS1 known as active agents in cancer progression, were identified as the central DEGs in the constructed PPI network in this study." (PMID 31528309, 2019). "AFF4 is reported to serve as a central binding platform for elongation factors in many SEC formations and to target MYC and regulate its expression in cancer cells." (PMID 24466310, 2014). "Furthermore, elevated IMPDH2 levels have demonstrated suppression of cancer cell apoptosis through the regulation of multifaceted pathways, including the PI3K/AKT/mTOR and PI3K/c-Myc/AFF4 pathways." (PMID 39085725, 2024).
tumor (15 papers, 2015 to 2025). "Here we report a case of BPDCN with a novel AFF4::IRF1 fusion predicted to lead to a loss-of-function of the IRF1 tumor suppressor, somatic mutations of ASXL1, TET2, and MYD88, as well as multiple intrachromosomal deletions." (PMID 38203475, 2023). "As shown, the CDH1 reconstitution in CRC cells with AFF4 depletion led to a deficiency of cell migration and invasion; hence, we confirmed that AFF4 served as a tumor suppressor in CRC metastasis via upregulating CDH1." (PMID 35223479, 2022). "AFF4 expression was stably ablated by short hairpin RNA (sh-AFF4) in 5637 cells, which were then injected subcutaneously into immune-deficient mice, and tumor growth was measured over time." (PMID 32676121, 2020). "Consistent with the in vitro results, AFF4-deficient cells exhibited a significantly lower tumor-propagating potential than the control cells (sh-GFP) comprising the tumor bulk." (PMID 32676121, 2020). "Taken together, aberrant expression of AFF4 is associated with BCSCs within the tumor bulk which may lead to poor prognosis." (PMID 32676121, 2020). "All TERT altered cases had elevated TERT expression with the highest expression observed in the AFF4:TERT fusion tumour." (PMID 40097403, 2025). "By contrast, silencing AFF4 promoted the proliferation, migration, and invasion of OC cells in vitro, suggesting that AFF4 played a tumor-suppressive role in OC." (PMID 34686190, 2021). "A possible reason is that AFF4, as a transcription factor, mainly activated tumor-suppressor genes or signaling pathways in OC; thus, the specific regulatory mechanism needs to be further explored." (PMID 34686190, 2021). "In consistence with previous report in which knockdown of TFAP2C decreased the number of cells in S phase and delayed the growth of xenograft tumor in both E2− and E2 + conditions, we observed a reduction of cell viability in all six AFF4-knockout lines." (PMID 32265480, 2020). "In addition, AFF4 promotes tumorigenesis and tumor-initiation capacity of head and neck squamous cell carcinoma and bladder cancer." (PMID 35223479, 2022). "We wondered whether AFF4 contributes to tumor growth or formation in vivo, as tumor growth supported tumor progression, such as metastasis." (PMID 35223479, 2022). "Further, AFF4, which acts as a tumor-suppressor gene in OC, was the new target for miR-425-5p." (PMID 34686190, 2021). "Furthermore, AF4/FMR2 family member 4 (AFF4), as a tumor-suppressor gene in OC, was the new target of miR-425-5p." (PMID 34686190, 2021). "Moreover, ALDH activity and sphere-forming ability in vitro as well as tumor-initiating capacity in vivo were all abrogated upon AFF4 knockdown." (PMID 32676121, 2020). "It is likely that METTL3 promote the expression of SOX2 and MYC through m6A-based posttranscriptional regulation as well as AFF4-mediated regulation at the transcriptional level, which reinforces the signal activating the tumor-initiating and self-renewal capabilities of BCa cells." (PMID 32676121, 2020). "AFF4 is also required for the tumor-initiating capacity of stem-like cells in HNSCC." (PMID 32676121, 2020). "In contrast, somatic mutations in tumor-promoting genes (FGFR1, RAC1, AFF3, AFF4, TSC2) may be intuitively associated with unfavorable prognosis." (PMID 30662871, 2018). "Such as, AFF4 upregulates SOX, which then promotes tumorigenesis and tumor-initiation capacity of head and neck squamous cells." (PMID 37063434, 2023). "AFF4 depletion impaired tumor formation, and rescued simultaneous expression of HPRT1 and IMPDH2 recovered tumor formation and tumor growth." (PMID 37063434, 2023). "Except our home collected patients’ samples, we again searched GEPIA database, which includes RNA sequencing expression data of 9736 tumor samples and 8587 normal samples from TCGA and GTEX, to compare the expression of AFF4 in CRC tissues and normal tissues." (PMID 35223479, 2022).
tumor (continued). "Mechanistically, METTL3 regulates the m6A modification and thereby the expression of AF4/FMR2 family member 4 (AFF4), knockdown of which phenocopies the METTL3 ablation and diminishes the tumor-initiating capability of BCSCs in vivo." (PMID 32676121, 2020). "In summary, we found m6A modification of AFF4 RNA was upregulated by METTL3 and their expression was elevated in BCSCs, which in turn promotes the expression of SOX2 and MYC to enhance tumorigenesis and tumor-initiating capacity of BCa." (PMID 32676121, 2020). "Furthermore, IHC was performed using an antibody against Ki67 and we observed that simultaneous expression of HPRT1 and IMPDH2 promoted tumor growth from cells lacking AFF4, proving a genetic axis of AFF4/HPRT1& IMPDH2 is existed in PDAC cells." (PMID 37063434, 2023). "We further examined the expression of AFF4 in CRC and adjacent tissues because exploring the tumor suppressor could be much more significant for tumor treatment as we have developed some methods to deliver tumor suppressor." (PMID 35223479, 2022).
hematologic malignancies (1 paper, 2022). "These preclinical studies have prompted the clinical testing of AZD4573 in hematologic malignancies and suggest that H3K27M-mutant tumors that are characterized by AFF4 upregulation are candidates for clinical CDK9 inhibition." (PMID 35567477, 2022).
neurodevelopmental disorder (1 paper, 2024). A behavioral and cognitive disorder with onset during the developmental period that involves impaired or aberrant development of intellectual, motor, or social functions. "Some of these genes themselves are of interest in brain development specifically, Nipa2 (non-imprinted in Prader-Willi/Angelman syndrome 2), Sez6 (seizure-related 6 homologs), and Aff4 (AF4/FMR2 family member 4) are involved in neurodevelopmental disorders with complex phenotypes." (PMID 37059894, 2024).
AFF4 also shares sentences with these, for which no sentence is quoted: skeletal dysplasia (3 papers); bladder tumor (2); Cornelia de Lange syndrome (2); glioma (2); Alpha-thalassemia (1); asthma (1); autism spectrum disorder (1); Azoospermia (1); bladder urothelial carcinoma (1); cardiomyopathy (1); cataract (1); chronic atrial and intestinal dysrhythmia syndrome (1); Cognitive impairment (1); colon carcinoma (1); colorectal tumor (1); diffuse intrinsic pontine glioma (1); gastric cancer (1); head and neck cancer (1); infection (1); Intellectual disability (1); KBG syndrome (1); osteosarcoma (1); ovarian carcinoma (1); retinoblastoma (1); Roberts-SC phocomelia syndrome (1); sarcoma (1); Warsaw breakage syndrome (1).